SPRR2D (small proline rich protein 2D)
Description:
Cross-linked envelope protein of keratinocytes. It is a keratinocyte protein that first appears in the cell cytosol, but ultimately becomes cross-linked to membrane proteins by transglutaminase. All that results in the formation of an insoluble envelope beneath the plasma membrane.
Tractability: Antibody: its Gene Ontology location is reachable by antibodies, with high confidence.
Gene: Protein-coding gene on chromosome 1 (153,039,732 to 153,041,931, reverse strand). Ensembl gene ENSG00000163216.
Subcellular location: Cytoplasm
Pathways (Reactome):
Developmental Biology: Formation of the cornified envelope
Gene Ontology:
Biological process: epidermis development
Cellular component: cytoplasm; cornified envelope; cytosol
Genetic constraint (gnomAD): Loss-of-function variants: 1 observed, 2.83 expected, observed/expected ratio (o/e) 0.35, 90% interval 0.12 to 1.52. That is too few expected variants to judge how well the gene tolerates losing a copy. Missense variants: 81 observed, 85.9 expected, observed/expected ratio (o/e) 0.94, 90% interval 0.79 to 1.13. Synonymous variants: 43 observed, 31.71 expected, observed/expected ratio (o/e) 1.36, 90% interval 1.06 to 1.74.
Homologues: Orthologues: chimpanzee SPRR2D (100% identical). Paralogues in human: SPRR2B (97% identical), SPRR2E (97% identical).
Diseases named in the same sentence as SPRR2D in open-access papers:
SPRR2D is named in the same sentence as 13 diseases in open-access papers, as found by Europe PMC text mining. Sharing a sentence is not in itself a finding about the gene and the disease. The quoted sentences say what the papers report.
cyst (3 papers, 2014 to 2020). A sac-like closed membranous structure that may be empty or contain fluid or amorphous material. "Upregulation of epigen, secretory leukocyte peptidase inhibitor (Slpi), and small proline-rich protein 2d (Sprr2d) in hair follicles was identified as the likely cause of infundibular acanthosis, hyperkeratosis, and cyst formation." (PMID 24503019, 2014). "Nrf2 activation in keratin 5 (K5)-positive skin epithelia leads to hair loss, infundibula dilatation, sebaceous gland enlargement, and cyst formation, with upregulation of Epigen, Slpi, and Sprr2d in the cyst." (PMID 33511139, 2020).
Hyperkeratosis (3 papers, 2014 to 2023). Hyperkeratosis is a histopathological term defining a thickened stratum corneum and may be present in many different skin conditions, with many possible overlaps. "Previous results demonstrated that a thickening of the epidermis, hyperkeratosis, and dilated infundibula are due to the upregulation of the expression of Slpi, Sprr2d, and Epgn (Epigen)." (PMID 37760426, 2023). "The increased expression levels of Slpi, Sprr2d, Nqo1, and Epgn in the affected epidermis and cutaneous cysts of a MADISH patient’s skin are reportedly mediated via follicular hyperplasia and hyperkeratosis, as evidenced by a prior study." (PMID 37760426, 2023).
psoriasis (3 papers, 2023 to 2024). An autoimmune condition characterized by red, well-delineated plaques with silvery scales that are usually on the extensor surfaces and scalp. "Interestingly, the association of SPRR2A and SPRR2D with psoriasis has been previously confirmed, supporting the relevance of our findings." (PMID 38596682, 2024). "Previous studies have shown that the LCE family and SPRR2D are involved in the pathogenesis of psoriasis by forming a tough structure beneath the cell membrane during the differentiation of keratinocytes." (PMID 37511476, 2023). "This analysis revealed the overexpression of SPRR2D, CD52, and PI3 in DCs isolated from psoriasis skin tissues." (PMID 38596682, 2024).
hepatocellular carcinoma (1 paper, 2021). A malignant tumor that arises from hepatocytes. "Similarly, we found that the level of SPRR2D transcript was correlated well with that of p73 transcript in both normal liver (Spearman’s r = 0.91) and hepatocellular carcinomas (Pearson’s r = 0.71)." (PMID 34204113, 2021).
lung carcinoma (1 paper, 2021). "Oncomine also showed, in our analysis, that SPRR1B and SPRR2D are overexpressed in lung cancer." (PMID 33501784, 2021). "Accordingly, we found that the expressions of SPRR1B and SPRR2D in multiple tumor data sets were higher in tumor tissues than in normal tissues (72 vs. 16 and 62 vs. 22, respectively), and the data sets with high expression in lung cancer were significantly more than those of other types of cancer." (PMID 33501784, 2021).
cancer (3 papers, 2018 to 2024). A tumor composed of atypical neoplastic, often pleomorphic cells that invade other tissues. "Moreover, the approach has also emphasized the importance of the small proline-rich protein family (SPRR), including SPRR2B, SPRR2E, and SPRR2D, recognized for their significant involvement in cancer-related pathways and their potential as therapeutic targets." (PMID 39000413, 2024). "Additionally, the GLMQL-MAS system highlighted the small proline-rich protein family (SPRR) including SPRR2B, SPRR2E, and SPRR2D, noted for their significant roles in cancer-related pathways and their potential as therapeutic targets." (PMID 39000413, 2024).
SPRR2D also shares sentences with these, for which no sentence is quoted: tumor (4 papers); breast carcinoma (1); cervical cancer (1); infection (1); leukemia (1); prostate carcinoma (1); squamous carcinomas (1).